PSPN (persephin)
Description:
Growth factor that exhibits neurotrophic activity on mesencephalic dopaminergic and motor neurons. Acts by binding to its coreceptor, GFRA4, leading to autophosphorylation and activation of the RET receptor.
Synonyms: PSP
Tractability: Antibody: UniProt places it where antibodies can reach, with high confidence; its Gene Ontology location is reachable by antibodies, with high confidence; UniProt predicts a signal peptide or a membrane-spanning region.
Gene: Protein-coding gene on chromosome 19 (6,375,148 to 6,379,058, reverse strand). Ensembl gene ENSG00000125650.
Subcellular location: Secreted
Pathways (Reactome):
Developmental Biology: NCAM1 interactions; RET signaling
Signal Transduction: RAF/MAP kinase cascade
Gene Ontology:
Molecular function: growth factor activity; signaling receptor binding; glial cell-derived neurotrophic factor receptor binding; receptor tyrosine kinase binding
Biological process: glial cell-derived neurotrophic factor receptor signaling pathway; central nervous system development; nervous system development; neuron projection development; system development
Cellular component: extracellular region
Genetic constraint (gnomAD): Loss-of-function variants: 16 observed, 10.5 expected, observed/expected ratio (o/e) 1.52, 90% interval 1.01 to 1.93. The synonymous counts are far from expectation, so gnomAD's model fits this gene poorly and the ratio says little. Missense variants: 229 observed, 185.05 expected, observed/expected ratio (o/e) 1.24, 90% interval 1.11 to 1.38. Synonymous variants: 115 observed, 83.16 expected, observed/expected ratio (o/e) 1.38, 90% interval 1.19 to 1.61.
Homologues: Orthologues: chimpanzee PSPN (97% identical), macaque PSPN (97% identical), guinea pig PSPN (81% identical), rabbit PSPN (75% identical), dog PSPN (73% identical), pig PSPN (71% identical), rat Pspn (67% identical), mouse Pspn (65% identical), tropical clawed frog PSPN (35% identical). Paralogues in human: ARTN (39% identical), NRTN (36% identical), GDNF (29% identical).
Diseases named in the same sentence as PSPN in open-access papers:
PSPN is named in the same sentence as 12 diseases in open-access papers, as found by Europe PMC text mining. Sharing a sentence is not in itself a finding about the gene and the disease. The quoted sentences say what the papers report.
breast carcinoma (1 paper, 2018). "This may reflect the extremely low expression of its co-receptor, GFRA4, in primary breast cancers, preventing PSPN from having much effect on breast cancer cells." (PMID 29608602, 2018).
disc degeneration (1 paper, 2023). "In the current study, the percentages of ARTN- and PSPN-expressing cells increased in the advanced stage of disc degeneration; however, the percentages of cells expressing their cognate co-receptors (GFRA3 and GFRA4, respectively) did not increase." (PMID 37958856, 2023).
glioma (1 paper, 2020). A benign or malignant brain and spinal cord tumor that arises from glial cells (astrocytes, oligodendrocytes, ependymal cells). "GDNF is a neurotrophic factor purified for the first time from a rat glioma cell line (B49) and belongs together with neurturin (NRTN), artemin (ARTN), and persephin (PSPN) to the family of GDNF ligands (GFL) belonging in turn to the superfamily of transforming growth factor β (TGF-β)." (PMID 33293946, 2020).
lung carcinoma (1 paper, 2019). "Genes AHCYL2 and PSPN were reported to be associated with lung cancer." (PMID 31640538, 2019).
metastatic disease (1 paper, 2021). "While MMP-7 inhibitors previously failed in clinical trials for treatment of metastatic disease, the findings reported here point to new avenues to interfere with downstream activation of dyscohesion and migration resulting from MMP-7 cleavage of the PSPN Complex." (PMID 33809984, 2021).
oral cancer (1 paper, 2020). "GFL member PSPN has been suggested to play a key role in human oral cancer progression." (PMID 32084217, 2020).
prostate carcinoma (1 paper, 2021). A carcinoma that arises from epithelial cells of the prostate gland. "The Perlecan-Semaphorin 3A-Plexin A1-Neuropilin-1 (PSPN) Complex at the cell surface of prostate cancer (PCa) cells influences cell–cell cohesion and dyscohesion." (PMID 33809984, 2021).
cancer (4 papers, 2021 to 2025). A tumor composed of atypical neoplastic, often pleomorphic cells that invade other tissues. "ARTN and NRTN genes are expressed most abundantly in osteoblastic OS cells, GDNF in carcinoma associated fibroblasts, and PSPN in endothelial cells." (PMID 40686838, 2025). "It was observed that the PSPN gene exhibited significant DE between myeloid cells 2 and carcinoma-associated fibroblasts (P-value = 1)." (PMID 40686838, 2025). "Our results showed that the PSPN gene exhibited no significant DE between plasmocytes and carcinoma associated fibroblasts (P-value = 1.611 ×10−1)." (PMID 40686838, 2025). "We observed that the PSPN gene exhibited no significant DE between carcinoma associated fibroblasts and endothelial cells (P-value = 2.7 × 10−1)." (PMID 40686838, 2025). "The PSPN gene was not DE between osteoclasts and carcinoma associated fibroblasts (P-value = 1.61 × 10−1)." (PMID 40686838, 2025). "We suggest that our findings reported here are most applicable to PCa tumors with a luminal PCS2 subtype, and perhaps a more aggressive luminal PCS1 subtype, and less relevant for cancers that already produce significant amounts of MMP-7 that can readily cleave the PSPN Complex components." (PMID 33809984, 2021). "Furthermore, the PSPN gene was not DE between osteoblastic OS cells and carcinoma-associated fibroblasts (P-value = 1)." (PMID 40686838, 2025). "Caco-2 cells express anti-angiogenic markers (i.e., persephin, angiopoetin-2, PDGF-AA and endostatin) upon exposure to 100 μg/mL TiO2NPs and could be a potential candidate for use in cancer therapy." (PMID 36291543, 2022). "As for GH1, PRKCG, and PSPN, they are not known prognostic biomarkers, but GH1 is still regarded as strongly related to cancer development because of its key role in the stimulation of growth factor secretion (i.e., IGF-1)." (PMID 36428747, 2022).
tumor (3 papers, 2016 to 2025). "IHC analysis with PSPN specific antibodies in sections from eight MLS tumors showed a cytoplasmic staining of the tumor cells in all cases." (PMID 26595521, 2016). "Our analysis of MLS cell lines showed that they contained mRNAs for glia derived neurotrophic factor (GDNF), neurturin (NRTN) and persephin (PSPN) but RNA extracted from tumor tissues contained only the PSPN transcript." (PMID 26595521, 2016). "Similarly, macrophages in metastatic UVM showed strong enrichment for cytokines like Adiponectin, Prolactin, IL7, IL10, IL15, IL9, IL31, APRIL, Persephin, and IL22, highlighting their role in creating a pro-tumorigenic environment through immune modulation and support of tumor growth." (PMID 39916959, 2024).
neurodegenerative disease (1 paper, 2022). A disorder of the central nervous system characterized by gradual and progressive loss of neural tissue and neurologic function. "PRKCG and PSPN have a function in neurodegenerative diseases." (PMID 36428747, 2022).
PSPN also shares sentences with these, for which no sentence is quoted: bacterial meningitis (1 paper); Parkinson disease (1).